HIF1A (hypoxia inducible factor 1 subunit alpha)
Diseases named in the same sentence as HIF1A in open-access papers (continued):
Sharing a sentence is not in itself a finding about the gene and the disease.
laryngeal carcinoma (continued). "It was suggested for patients with early-stage laryngeal carcinomas displaying a high expression of HIF-1α, treatment modalities alternative to primary radiotherapy should be considered in these cases." (PMID 30840126, 2019). "In the present study, the results showed that simultaneous inhibition of GLUT-1 and HIF-1α increased necrosis more effectively than did inhibition of GLUT-1 or HIF-1α alone in laryngeal cancer." (PMID 28410229, 2017). "In our previous study, the expression of GLUT1 and HIF1α was significantly correlated with 18F-FDG uptake in patients with laryngeal carcinoma." (PMID 28410229, 2017). "Hypoxia-inducible factor 1α (HIF-1α) and glucose transporter-1 (GLUT-1) are two important hypoxic markers associated with the radioresistance of cancers including laryngeal carcinoma." (PMID 28410229, 2017). "In the present study, the results showed that simultaneous inhibition of GLUT-1 and HIF-1α decreased MVD more effectively than did inhibition of GLUT-1 or HIF-1α alone in laryngeal cancer." (PMID 28410229, 2017). "GLUT and HIF-1α expression was also compared with the pTNM classification of laryngeal cancer cases, since the tumor stage is currently the only accepted prognostic marker." (PMID 25412955, 2015). "The aim of this study was to examine the predictive value of GLUT1, GLUT3, and HIF-1α messenger RNA (mRNA)/protein expression as markers of tumor aggressiveness and prognosis in laryngeal cancer." (PMID 25412955, 2015). "In the present study, 58.3% (14/24), 50.0% (12/24), 29.2% (7/24) and 54.2% (13/24) of the laryngeal carcinomas were positive for Glut-1, HIF-1α, PI3K and p-Akt protein, respectively." (PMID 24944654, 2014). "As a key nuclear transcription factor, HIF-1α exerts a positive regulatory effect on MDR1 gene expression in response to hypoxia in laryngeal cancer Hep-2 cells." (PMID 23946810, 2013). "In this case, increased GLRX expression and impaired mitochondrial activity may collectively regulate the oxidative and hypoxic behavior (i.e., increased HIF1A) exhibited by the resistant laryngeal cancer cells." (PMID 40385549, 2025). "Additionally, in laryngeal carcinoma cell cultures, HIF-1α upregulates the expression of Survivin, a member of an inhibitor-apoptosis protein family." (PMID 36140250, 2022). "HIF‐1α and/or Glut‐1 could be promising candidates for improving radiosensitivity in laryngeal carcinoma." (PMID 35415942, 2022). "Double knockout of Glut‐1 and HIF‐1α may be a novel strategy for enhancing radiosensitivity in laryngeal carcinoma." (PMID 35415942, 2022). "In addition, double knockout of Glut‐1 and HIF‐1α led to greater radiosensitivity in laryngeal carcinoma cells under hypoxic conditions, compared with single gene knockouts." (PMID 35415942, 2022). "We evaluated whether the simultaneous inhibition of GLUT-1 and HIF-1α expression improved the radiosensitivity of laryngeal carcinoma." (PMID 28410229, 2017). "However, the role of HIF-1α activity in laryngeal cancer is poorly understood, and very few studies regarding HIF-1α in Indonesian laryngeal cancer patients have been published." (PMID 27882053, 2016). "We have previously reported that there is a significant correlation between GLUT-1 and HIF-1α expression in laryngeal carcinoma, and there is further evidence thatthe phosphatidylinositol 3-kinase (PI3K)/protein kinase B (Akt) pathwaymay regulate HIF-1α and GLUT-1." (PMID 24980293, 2014). "Immunostaining for HIF-1α was observed in 56 (65.1%) of the 86 laryngeal cancer tissues." (PMID 23946810, 2013). "However, it remains unclear whether double knockout of Glut‐1 and HIF‐1α using the CRISPR/CAS9 technique affects radiosensitivity in laryngeal carcinoma." (PMID 35415942, 2022). "Moreover, HIF-1α may upregulate GLUT-1 expression in laryngeal carcinoma leading to chemo-resistance." (PMID 36140250, 2022).
laryngeal carcinoma (continued). "Thus, HIF‐1α regulation may mediate reversal of the effects of hypoxia and provide a novel therapeutic strategy to enhance radiosensitivity in laryngeal carcinoma." (PMID 35415942, 2022). "Thus, Glut‐1 and HIF‐1α knockout contributed to radiosensitivity in laryngeal carcinoma cells." (PMID 35415942, 2022). "There were significant correlations between SUVmax and Glut-1 (r=0.577; P=0.003), HIF-1α (r=1.0; P<0.0001), PI3K (r=1.0; P<0.0001) and p-Akt (r=0.577; P=0.003) expression, indicating that a high FDG uptake was significantly associated with a poor outcome in laryngeal carcinoma." (PMID 24944654, 2014). "After a deeper analysis of the proangiogenic expression profile in laryngeal carcinoma, we identified a specific subgroup of patients with overexpression of VEGF-A (RQ > 2) and normal/downregulated expression of HIF1α (RQ < 2)." (PMID 41359448, 2026). "In another study, we investigated the expression of HIF-1α, GLUT-1, and proteins of the PI3K/Akt pathway in 24 tissue samples from patients with laryngeal carcinoma who received PET/computed tomography (CT) preoperatively." (PMID 31105886, 2019). "We also investigated the relationship between HIF-1α or GLUT-1 expression and clinicopathological features or prognosis in 49 tissue samples of laryngeal carcinoma." (PMID 31105886, 2019). "For instance, simultaneous inhibition of HIF-1α and GLUT-1 expression was able to increase the radiosensitivity of laryngeal cancer." (PMID 29930482, 2018). "In this study, we assessed the effect of simultaneous inhibition of HIF-1α and GLUT-1 expression on radioresistance in laryngeal carcinomas in vivo." (PMID 28410229, 2017). "In this study, we evaluated the radiosensitivity of laryngeal carcinoma using micro PET/CT and assessed the relationships between HIF1α, GLUT1-1 expression and 18F-FDG uptake in vivo." (PMID 28410229, 2017). "After transfection of siRNA against HIF-1α, both hypoxia- and radiation-induced INPP4B expression decreased, indicating that such expression is increased by HIF-1α in laryngeal carcinoma Hep-2 cells." (PMID 27823965, 2017). "Positive expression of SLC2A1, SLC2A3, and HIF-1α genes was noted in 83.9, 82.1, and 71.7 % of SCC specimens and in 34.4, 59.4, and 62.5 % of laryngeal cancer samples." (PMID 25412955, 2015). "Also, because of the limited amount of biological material in our study, GLUTs and HIF-1α were compiled with regard to protein expression only, with pTNM classification, the currently accepted prognostic parameters, being used in a smaller number of laryngeal cancer cases." (PMID 25412955, 2015). "Besides, genes from molecular pathways of autophagy (ULK/ATG complex), drug efflux (ABC transporters), mitochondrial activity (V‐ATP synthase), hypoxia (HIF1A), and PI3K/mTOR (PIK3CA, CASTOR1, and DEPTOR) were upregulated in resistant laryngeal cancer cells." (PMID 40385549, 2025). "Despite the fact that most malignancies display the characteristics of a HIF switch, our team has already shown the predominating role of HIF1-α in laryngeal carcinoma, e.g., the lack of such an HIF switch." (PMID 38607072, 2024). "In summary, we observed a canonical proangiogenic phenotype in advanced laryngeal cancer with a significant upregulation of HIF-1α but not HIF-2α, i.e., HIF switch was not evident." (PMID 38607072, 2024). "Simultaneous inhibition of HIF-1α and GLUT-1 expression might increase the radiosensitivity of laryngeal carcinoma, decreasing MVD, and promoting apoptosis and necrosis." (PMID 28410229, 2017). "Unfortunately, the role of HIF-1α in the regulation of MDR1 gene expression in laryngeal cancer cells under hypoxic conditions has not yet been clarified." (PMID 23946810, 2013). "Some studies found an association between local control after initial treatment with radiotherapy and CA-IX or HIF-1α in patients with laryngeal cancer, while others could not confirm this." (PMID 37029804, 2023).
laryngeal carcinoma (continued). "Thus, the role of HIF-1α in laryngeal carcinoma radioresistance and whether inhibition of HIF-1α expression can improve radiosensitivity of laryngeal carcinoma require further evaluation." (PMID 28410229, 2017). "Moreover, laryngeal cancers with TFG total score ≥14 points, deep invasion (3–4 points), and disseminated growth (3–4 points) were noted to have significantly higher HIF-1α gene level compared to less invasive tumors (p < 0.001, p < 0.001, and p < 0.001, respectively)." (PMID 25412955, 2015). "The expression of HIF-1α and PI3K was associated with survival time in the univariate analyses, and PI3K continued to be a prognostic factor in the multivariate analysis, while the other markers (Glut-1 and p-Akt) were not directly associated with survival time in patients with laryngeal carcinoma." (PMID 24944654, 2014). "Therefore, the correlation between FDG uptake and the hypoxia markers, Glut-1, HIF-1α, PI3K and Akt, was investigated in the present study using immunohistochemistry to clarify whether FDG-PET can be used to predict tumor hypoxia and the prognosis of patients with laryngeal carcinoma." (PMID 24944654, 2014). "As yet, studies have not demonstrated a correlation between the HIF-1α protein and MDR1 gene expression in human laryngeal cancer." (PMID 23946810, 2013). "The majority of patients expressed a canonical HIF-upregulated proangiogenic signature with almost complete predominancy of mRNA HIF-1α overexpression and normal expression levels of the mRNA HIF-2α isoform, i.e., HIF switch was not present in advanced laryngeal cancer." (PMID 38607072, 2024).
periodontitis (25 papers, 2015 to 2026). An acute or chronic inflammatory process that affects the tissues that surround and support the teeth. "Still, the level of salivary HIF-1α was significantly higher in the periodontitis group than in the control group, with excellent diagnostic ability to distinguish between periodontitis and periodontal health." (PMID 38744330, 2025). "Periodontitis results in a notable elevation in HIF-1α salivary levels, with an outstanding diagnostic ability to distinguish between periodontitis and periodontal health." (PMID 38744330, 2025). "This study sought to examine the association between HIF-1α SNP and periodontitis and assess the presence of disparities in HIF-1α levels between persons with periodontitis and those who are healthy." (PMID 38744330, 2025). "Proanthocyanin, a potent grape seed antioxidant, has been reported to reduce inflammation and alveolar bone loss due to periodontitis by decreasing HIF-1α and MMP-8 levels and increasing osteoblast activity in diabetic rats periodontitis." (PMID 37501927, 2023). "HIF1A, involved in cellular responses to oxidative stress, has been implicated in the immune-inflammatory response in periodontitis and is also upregulated in H. pylori-mediated gastric inflammation and carcinogenesis." (PMID 35132337, 2022). "The expression level of the hypoxia marker HIF‐1α and the oxidative stress marker 8‐OHdG were both increased with the Dec2 deficiency during periodontitis." (PMID 33270996, 2021). "Considering the adverse consequences of hypoxia on human physiology,9, 11, 12and the crucial involvement of HIF-1α in the development of periodontitis,22, 23, 24, 25further studies are needed to recognize the effects of hypoxia associated with periodontitis on the levels of HIF-1α in saliva." (PMID 38744330, 2025). "In conclusion, our present data demonstrated that butyrate-induced ferroptosis may contribute to the loss of PDLFs during periodontitis development, and the onset of ferroptosis involves p38/HIF-1α activation and BRD4/CDK9 coordination." (PMID 33298848, 2020). "The AUC for salivary HIF-1α was 0.913, with an excellent ability to differentiate periodontal health from periodontitis." (PMID 38744330, 2025). "Ng et al13were the first to provide evidence of elevated HIF-1α expression in periodontal tissues affected by periodontitis." (PMID 38744330, 2025). "The periodontitis group showed significantly higher salivary HIF-1α levels compared to control group (p < 0.001)." (PMID 38744330, 2025). "Studies have observed an increase in HIF-1α protein expression in gingival tissue specimens obtained from patients diagnosed with periodontitis." (PMID 38744330, 2025). "Concerning the salivary level of HIF-1α, the significantly highest value was found in the periodontitis group." (PMID 38744330, 2025). "Immunofluorescence staining of periodontal tissues confirmed elevated HIF‐1α expression in periodontitis patients compared to healthy controls." (PMID 41020683, 2025). "LINC01126 promotes the pathogenesis of periodontitis in human periodontal membrane cells via the miR‐518a‐5p/HIF‐1α/MAPK pathway, providing possible clues for LINC01126‐based therapeutic approaches for periodontal disease." (PMID 36525280, 2023). "The expression level of HIF-1a was significantly induced in periodontal tissue of the periodontitis group compared with the control group, which indicates the hypoxic microenvironment." (PMID 38040672, 2023). "We found that periodontitis increased HIF-1α protein expression in gingival tissue (P < 0.05), and a similar result was also observed in the PS group rats (P < 0.05)." (PMID 35221795, 2022). "In this study, increased expression of HIF-1α and substance P was observed in rat ligation-induced experimental periodontitis, which revealed that both factors participate in periodontitis." (PMID 32000757, 2020). "Another study showed that HIF-1α seemed to be involved in the induction, progression, and persistence of periodontitis." (PMID 32000757, 2020).
periodontitis (continued). "We will carry out the relevant experiments in future studies to investigate the mechanisms of substance P and HIF-1α in periodontitis." (PMID 32000757, 2020). "Ligation-induced rat periodontitis was established to observe the distribution and expression of substance P and HIF-1α by immunohistochemistry." (PMID 32000757, 2020). "Western blotting showed that the gingiva in periodontitis expressed higher HIF-1α compared with that of normal gingiva (*P < 0.05)." (PMID 32000757, 2020). "Periodontal tissue sections (healthy gingiva and periodontal ligament (PDL), gingivitis, and periodontitis) were obtained from three different patients for each group and immunohistochemistry for HIF-1α was performed." (PMID 25861162, 2015). "Nevertheless, this study found elevated levels of salivary HIF-1α with excellent diagnostic ability for periodontitis regardless of the existence of a significant risk factor, which is smoking." (PMID 38744330, 2025). "Yet, the results of multiple linear regression revealed a nonsignificant association of A207C SNP with periodontitis as well as with salivary levels of HIF-1α level." (PMID 38744330, 2025). "However, the sequencing results of the 352 bp of the HIF-1α gene revealed the presence of 144 SNPs in total (66 SNPs in control samples, whereas 78 SNPs were found in periodontitis sample)." (PMID 38744330, 2025). "They found that VEGF-A mRNA and protein levels were elevated in large osteoclasts, found mostly in MRONJ and periodontitis specimens, compared to small osteoclasts, and that this increase was regulated by HIF-1α, whose mRNA levels were induced by RANKL-mediated activation of NF-κB." (PMID 36979736, 2023). "In gingival biopsies from periodontitis subjects (in a hypoxic pathological context), the fibroblast-like cells and infiltrating inflammatory cells overexpress HIF-1α, suggesting that the HIF pathway is involved in the inflammatory response of human periodontal tissue." (PMID 36142220, 2022). "Interestingly, in the present study, we found that CUMS had a similar effect as periodontitis in terms of increasing HIF-1α protein expression and ROS generation in periodontal tissue." (PMID 35221795, 2022). "Additionally, the combination of stress and periodontitis had synergistic adverse effects on periodontal HIF-1α protein expression, local redox state, and NF-κB activation." (PMID 35221795, 2022). "Applying a HIF-1α antagonist may be helpful for interpreting the relationship between HIF-1α and substance P in periodontitis and observing the role of substance P in osteoclast differentiation." (PMID 32000757, 2020). "The roles of HIF-1α in periodontitis should be further studied." (PMID 32000757, 2020). "Higher HIF-1α levels were observed in periodontitis compared to that of normal tissues." (PMID 32000757, 2020). "Substance P participates in periodontitis by upregulating HIF-1α and the RANKL/OPG ratio." (PMID 32000757, 2020). "More attention should be paid to the roles of HIF-1α in periodontitis and further study is needed." (PMID 32000757, 2020). "Besides, HIF-1α is a good biomarker in distinguishing between periodontal health and periodontitis." (PMID 38744330, 2025). "Substance P might participate in periodontitis by upregulating HIF-1α." (PMID 32000757, 2020). "Tissue hypoxia in periodontal disease is characterized by an increase in hypoxia-inducible factor 1-alpha (HIF-1α) protein levels, which is detectable in tissue biopsies affected by periodontitis." (PMID 36983008, 2023). "The present study aimed to explore the expression of inflammatory hypoxia-related miRNAs (miRNA-20a, miRNA-30e, and miRNA-93), and miRNA target genes, HIF-1α and NFAT5, in periodontitis and healthy gingival tissues." (PMID 36142220, 2022). "HIF1A/HIF1, an oxygen-regulated subunit, is involved in the immune response of periodontitis, playing a pleitropic role in defending against macrobiotics and facilitating the progression of periodontitis." (PMID 33777111, 2021).